TXNIP (thioredoxin interacting protein)
Diseases named in the same sentence as TXNIP in open-access papers (continued):
Sharing a sentence is not in itself a finding about the gene and the disease.
tumor (continued). "TXNIP was identified as a tumor suppressor in many cancers and its downregulation was proposed to promote EMT and cancer metastasis." (PMID 38890620, 2024). "In support of this, analysis of the TCGA COAD (CRC) database showed decreased TXNIP mRNA in tumor samples compared to normal controls." (PMID 39103698, 2024). "We subsequently assessed the proliferation potential of the cells in vivo.We observed that the subcutaneous tumor volume in nude mice was noticeably smallerfollowing overexpression of the TXNIP gene than in the control group." (PMID 38229544, 2024). "TXNIP is considered to be involved in tumor suppression by negatively regulating the function of the TRX system, increasing oxidative stress, and regulating immune cells." (PMID 39526479, 2024). ".Therefore, we propose that TXNIP inhibits the activation of the MAPK signaling pathway bysuppressing the phosphorylation of the Erk1/2 protein in tumor cells, thereby inhibitingtumor cell proliferation." (PMID 38229544, 2024). "TXNIP can inhibit tumor cell growth and metastasis by suppressing metabolic reprogramming and promoting oxidative stress." (PMID 38244591, 2024). "Our resultshighlighted the key role of TXNIP in suppressing tumor cell proliferation and mitigatingmetastasis." (PMID 38229544, 2024). "Here, we describe context-dependent suppression of tumor cell glycolysis by Dpep, the mechanisms by which this occurs via suppression of glucose uptake by upregulation of the tumor suppressor TXNIP and its relevance to promotion of apoptotic death." (PMID 38920655, 2024). "TXNIP is relatively well-studied in cancer and has been reported to have tumor-suppressive effects as discussed." (PMID 39103698, 2024). "In CRC, TXNIP expression has been observed to be decreased in tumor cases compared to normal tissues." (PMID 39103698, 2024). "Further study implied that TXNIP can increase ROS levels and cause DNA damage, leading to the apoptosis of DOX-resistant tumor cells." (PMID 39061897, 2024). "To further elucidate the specific mechanisms by which TXNIP influences tumor cellproliferation, we employed RNA sequencing (RNA-seq) to analyze the impact of TXNIPoverexpression on the gene expression profiles of PANC-1 and SW1990 cells." (PMID 38229544, 2024). "Previously, strong TXNIP staining was seen in the nuclei of endothelial cells of tumour supporting capillary meshwork in 512 of 691 cRCC occurring the general population." (PMID 39020292, 2024). "We foundthat tumor diameter (HR=1.471, P=0.014) and TXNIP expression (HR=0.708, P=0.029) were independent predictors of OS." (PMID 38229544, 2024). "Our interest in TXNIP stemmed from its reported role in regulating epithelial oxidative stress and our observation of its increased expression in fresh tumor samples after oxaliplatin treatment." (PMID 39103698, 2024). "According to a recent study, miR-106b promoted the proliferation of MF tumor cells by repressing the tumor suppressors p21 and TXNIP." (PMID 39256366, 2024). "Specifically, the expression of SLC2A1 in tumor tissues exhibited a remarkable increase, whereas the expression of TXNIP demonstrated a noteworthy decrease." (PMID 39526479, 2024). "We also observed an increase in the phosphorylation level of theErk1/2 protein in tumor cells after TXNIP knockdown." (PMID 38229544, 2024). "The DCIS gradually loses expression of thioredoxin interacting protein (TXNIP) which is a growth/tumor suppression protein and gains expression of legumain, which is a proliferation protein." (PMID 39684874, 2024). "The frequency, increased level and cellular localisation of TXNIP/TXN in tumours of ESRD/ACRD kidneys versus tumours of the general population suggests their role in ESRD/ACRD tumorigenesis." (PMID 39020292, 2024). "Given the importance of the innate immune system in developing and maintaining the TME, this suggests to us that low environmental TXNIP is important in allowing for tumor development." (PMID 37794178, 2023).
tumor (continued). "Led by the literature, we pay particular attention to the roles of TXNIP in redox, metabolic and immunological control of tumor biology." (PMID 37794178, 2023). "The tumor suppressive role of TXNIP through negative regulating glucose metabolism has been reported broadly." (PMID 37095099, 2023). "Of note, induced expression of TXNIP strongly inhibited malignant T-cell proliferation, indicating that TXNIP acts as a potential tumor suppressor in CTCL." (PMID 36761972, 2023). "Due to the fact that induced TXNIP expression inhibits the proliferation of malignant T cells, it has been suggested as possible tumor suppressor in CTCL." (PMID 36761972, 2023). "Concerning the association of TOMM34 to cancer, another significantly upregulated gene, TXNIP (log2FC = 2.86), has been shown to perform tumor suppressor function in several cancer cell types." (PMID 36829477, 2023). "Exosomes and TXNIP also have an intimate relationship as several miRNAs shuttled in exosomes mediate TXNIP downregulation, which can complement the effects of cytokines in the tumor microenvironment." (PMID 37794178, 2023). "In conventional RCC, immunohistochemical staining of 691 patient samples revealed that patients with high TXNIP expression have a marked reduction in tumor free survival and a higher occurrence of metastasis." (PMID 37794178, 2023). "TXNIP levels were highly increased in tumor tissue treated with pevonedistat and combination therapy." (PMID 36860653, 2023). "So far, more and more evidence identified that TXNIP functions as a tumor suppressor via the inhibition of glucose uptake and aerobic glycolysis." (PMID 37095099, 2023). "The molecular mechanisms of TXNIP regulation of cell cycle, inflammation and glycolysis can have tremendous consequences on both tumor and immune cells." (PMID 37794178, 2023). "By impacting different immune cell in different ways, TXNIP can drive both antitumor and pro-tumor effects." (PMID 37794178, 2023). "The mechanism by which tumor-infiltrating NK cells gain resistance to oxidative stress is through retention of nuclear TXNIP leading to higher Trx-1 activity." (PMID 37794178, 2023). "Intriguingly, TXNIP, which was verified the tumor suppressive role in several types of tumors in our previous studies, was uncovered decreased in K562G cells." (PMID 37095099, 2023). "Further, TXNIP expression decreases with increasing tumor grade, and low TXNIP expression is correlated with poor clinical outcomes in several cancers." (PMID 36930677, 2023). "Only two transcripts, MARCKS (Myristoylated Alanine Rich Protein Kinase C Substrate) and TXNIP (Thioredoxin Interacting Protein) were present in all three gene sets in the C2 tumor cell cluster." (PMID 36788228, 2023). "First, two tumor suppressors caught our attention: the thioredoxin-interacting protein TXNIP and the cell adhesion molecule CADM4." (PMID 37367050, 2023). "The study goes on to demonstrate that the high expression of TXNIP in TAMs contributes to metabolic changes which are required for macrophage polarisation and the promotion of pro-tumor responses." (PMID 37794178, 2023). "In this review, our focus is less on deciphering TXNIP’s prognostic impact but more on the role of TXNIP within the tumor microenvironment (TME), including both tumor cells and host cells, and its impact on different cancer hallmarks." (PMID 37794178, 2023). "As an intracellular amplifier of oxidative stress and inflammasome activation, TXNIP is detected in different cell types (such as tumor cells, immune cells and stromal cells)." (PMID 37794178, 2023). "MiR-532 directly targeted and inhibited E2F1 expression, leading to the decrease of ASK1 and elevation of TXNIP, and affected proliferation, cell cycle, apoptosis and DNA damage in vitro and tumor growth in vivo." (PMID 35440106, 2022). "Immunohistochemical score of TXNIP showed that the expression level of TXNIP in tumor tissues was significantly lower than that in paired normal tissues (P = 0.0003)." (PMID 35843949, 2022).
tumor (continued). "TXNIP is a thioredoxin-binding protein involved in redox regulation and glucose uptake that functions as a tumor suppressor gene." (PMID 36137002, 2022). "Altogether, our study provides insights in understanding the potential role of TXNIP in tumor immune microenvironment and its possible application in tumor immunotherapy." (PMID 35843949, 2022). "The genetic alteration status of TXNIP in different tumor samples of the TCGA cohorts was examined by the cBioPortal website." (PMID 35843949, 2022). "The expression of TXNIP is at a low level in these tumor types, and the overexpression of TXNIP inhibits the proliferation of cancer cells." (PMID 36428626, 2022). "GADD45A acts as a proapoptotic protein that induces apoptosis and cell cycle arrest, and TXNIP is an effector in glucose metabolism and can thus inhibit tumor cell proliferation through glucose metabolism." (PMID 35915803, 2022). "Further, western blotting analysis of 18 pairs of randomly selected CRC samples showed that tumor tissues exhibited markedly lower level of TXNIP than the adjacent tissues (P = 0.0133)." (PMID 35843949, 2022). "This role is supported by studies showing that TXNIP downregulation is a prerequisite for cell division and that TXNIP functions as a bona fide tumor suppressor." (PMID 36291127, 2022). "TXNIP is thought to play a role in tumor suppression by impeding cellular glucose uptake and increasing oxidative stress." (PMID 36366411, 2022). "Since TXNIP is a potent tumor inhibitor, it is frequently discovered that it is expressed at low concentrations across several tumor types." (PMID 36366411, 2022). "Among the upregulated genes, MBNL2, SEPT4, REPS2, OTUD5, and TXNIP were shown to play a tumor-suppressive role in many tumors." (PMID 36428626, 2022). "Significantly reduced TXNIP expression has been observed in numerous tumors, suggesting its function as a tumor suppressor." (PMID 36366411, 2022). "This was unexpected, as TXNIP is often referred to as a tumor suppressor as its expression is markedly downregulated in various tumors, while overexpression of TXNIP inhibits proliferation of cancer cells." (PMID 36232644, 2022). "TXNIP was lowly expressed in 12 out of 22 tumor tissues and highly expressed in 19 out of 22 normal tissues." (PMID 35843949, 2022). "In multivariate analysis, in addition to TXNIP positivity, tumour necrosis was presented as independent prognostic factor of postoperative tumour relapse (p = 0.004)." (PMID 34433833, 2021). "TXNIP is a potent negative regulator of glucose uptake and aerobic glycolysis, and its mRNA level is commonly reduced in diverse tumor types." (PMID 32683582, 2021). "We showed in this study that the highest expression of TXNIP protein occurred in tumour areas with small circumscribed tumour cell necrosis." (PMID 34433833, 2021). "In the second group of tumours with medium or high TXNIP expression in tumour cells only few vessels has been recognized." (PMID 34433833, 2021). "The translocation of TXNIP into the nuclei of endothelial cells of tumour supporting vessels indicates an increased level of ROS." (PMID 34433833, 2021). "Conversely, other studies have emphasized reduced TXNIP expression in tumor cells, mostly solid cancers." (PMID 33803178, 2021). "Re-introduction of TXNIP attenuated the metabolic reprogramming induced by the Ct-HBx and inhibited the tumor growth in the mice model." (PMID 33323975, 2021). "miR-106b can promote tumor proliferation in vitro by inhibiting the tumor suppressor p21 and thioredoxin-interacting protein." (PMID 34966672, 2021). "The expression of TXNIP was hardly detected in tumor xenografts induced by the truncated HBx-expressing cells." (PMID 33323975, 2021). "Taken together, these findings suggest that TXNIP is a potential tumor-suppressing gene, which can be downregulated by Ct-HBx." (PMID 33323975, 2021). "TXNIP was recognized as a tumour suppressor in cells as it can interact with Trx by blocking its biological function." (PMID 33451071, 2021).
tumor (continued). "In vivo mice xenograft growth assay exhibited that re-introduction of TXNIP successfully inhibited tumor growth as compared with the control group." (PMID 33323975, 2021). "Supporting the tumor suppressive effects of TXNIP and MAGI1, we found that knockdown of TXNIP or MAGI1 in ASXL1+/− K562 cells led to increased proliferation and higher cell viability under serum deprivation." (PMID 32683582, 2021). "The tumor-suppressive role of TXNIP via modulating metabolic reprogramming has been studied in pancreatic cancer and breast cancer." (PMID 33323975, 2021). "On the other hands, lack or reduced expression of TXNIP in cancer cell lines, experimental mouse models as well as in tumour tissues suggested that TXNIP is a tumour suppressor gene." (PMID 34433833, 2021). "The Kaplan–Meier survival analysis indicated that patients with tumours dysplaying cytoplasmic TXNIP protein expression have significantly shorter tumour free survival (p < 0.001)." (PMID 34433833, 2021). "The majority of TXNIP positive tumours displayed unorganized, irregular or tortuous tumour vessels as compared to those seen in well differentiated cRCC." (PMID 34433833, 2021). "TXNIP has long been recognized as a potential tumor suppressor gene that inhibits cell growth and is involved in stress response, REDOX regulation, and cell proliferation." (PMID 34324544, 2021). "As vascular TXNIP expression has been detected in all tumours analysed in this cohort, we evaluated only the cytoplasmic TXNIP expression in relation of tumour the progression." (PMID 34433833, 2021). "The TXNIP expression in tumour cells was significantly correlated with tumour size, grade and T-classification and tumour necrosis as well as postoperative progression of cRCCs (all p < 0.001)." (PMID 34433833, 2021). "TXNIP is a thioredoxin-interacting protein and has been reported to induce arrest of cell cycle, which acts as a tumor suppressor." (PMID 32657760, 2020). "High cytoplasmic TxNIP expression was linked with GBM (χ2 = 9.362, df = 2, P = 0.009), supratentorial tumours (χ2 = 5.314, df = 2, P = 0.021) and higher tumour grade (χ2 = 7.923, df = 1, P = 0.005)." (PMID 32418115, 2020). "Although there appears to be selective pressure against TXNIP for distant metastasis, its roles during primary tumor growth and peritoneal metastasis remain undefined." (PMID 32792504, 2020). "Using immunohistochemical staining for TXNIP in different tumor entities, we give new insights of TXNIP expression on the protein level." (PMID 33081035, 2020). "Downregulation of TXNIP promotes tumor proliferation, migration, and metastasis by remodeling of extracellular matrix." (PMID 32511893, 2020). "Overexpression of TXNIP has been correlated with inhibition of tumor cell suppression in multiple studies." (PMID 33302545, 2020). "miR-27a-3p targets the 3′UTR in TXNIP to downregulate TXNIP expression, thereby promoting the tumor proliferation and migration in RCC." (PMID 33194655, 2020). "Our findings demonstrate that TXNIP downregulation is a common feature in human tumor xenograft models." (PMID 33081035, 2020). "As TXNIP protein expression has only been investigated in few malignancies, we employed immunohistochemical detection in a large multi-tumor tissue microarray consisting of 2,824 samples from 94 different tumor entities." (PMID 33081035, 2020). "In summary, this study provides insights into the molecular mechanism of TXNIP‐mediated tumor suppression and furthermore underscores the potential of TXNIP as a promising therapeutic target for MLL‐r AML." (PMID 32511893, 2020). "It has also been shown that TXNIP overexpression in T238 cells inhibits tumor growth and decreases metastasis in a mouse model of in situ thyroid cancer." (PMID 33194655, 2020). "TXNIP has also been identified as a tumour suppressor, and is often observed to be downregulated in cancer." (PMID 32138149, 2020).
tumor (continued). "In conclusion, these findings suggest that TXNIP downregulation is as a common feature in human tumor xenograft models and that intra-tumoral leukocytes down-regulate TXNIP." (PMID 33081035, 2020). "TXNIP was proposed to be a tumor suppressor, which can be recapitulated for some tumor entities analyzed on our TMA." (PMID 33081035, 2020). "Through this signalling pathway, the tumorigenic ability of TRAF6 can be alleviated by crosstalking a tumor suppressive gene TXNIP, leading to a decline in tumogenesis." (PMID 31578830, 2020). "The TXNIP was suggested to be used as a prognostic marker as its expression inversely correlates with the pathological grade of tumor, while its overexpression can indicate a longer survival of cancer patients." (PMID 33228209, 2020). "Consistent with the role of SAM as a methyl donor, NCT-503 decreased DNA and histone methylation, and led to the re-expression of ID4, KLF4, CDKN2B and TXNIP tumor suppressors." (PMID 32138178, 2020). "We also tested the cell proliferation via nude mice xenograft experiment, we observed nude mice injected the cells expressing TXNIP sh4 had larger tumor size than that of cells expressing TXNIP sh4/TRAF6 sh34." (PMID 31578830, 2020). "Studies have also shown that mTOR and HDAC inhibitors act by converging on the TXNIP antioxidant pathway to co-affect chromatin and transcription, resulting in the death of aggressive neurological malignancies and tumor shrinkage." (PMID 33194655, 2020). "Thioredoxin-interacting protein (TXNIP) is a member of the alpha-arrestin protein family that binds to the active site and counteracts the action of Trx1 functioning as tumor suppressor." (PMID 31652503, 2019). "With regards to cancer, TXNIP is proposed to be a potential tumor suppressor due to its ability to induce oxidative stress-mediated apoptosis, as well as due to its reduced expression and silencing in tumor tissues and cancer cell lines." (PMID 29534438, 2018). "To understand the role of TXNIP on anchorage-dependent growth, differentiation, and morphogenesis of tumor cells, we performed branching morphogenesis assays." (PMID 30627326, 2018). "Sinusoidal/stromal TXNIP expression in HCC cases positively correlated with intrahepatic vascular invasion away from the tumor (p:0.0400)." (PMID 30627326, 2018). "E2F2 acts as a tumor suppressor by modulating apoptosis via the suppression of Myc-induced proliferation and tumorigenesis, while TXNIP has been shown to act as a tumor suppressor in thyroid cancer." (PMID 29434270, 2018). "TXNIP is a well‐known tumor suppressor and pro‐oxidant protein that inhibits TRX activity via direct interaction with the catalytic active center of TRX." (PMID 30168649, 2018). "Here we describe a temporal analysis of an in vitro PM model system to describe a novel bimodal gene, TXNIP, which helps provide insight into the molecular switches that drive a tumor to peritoneal dissemination." (PMID 30479697, 2018). "Thioredoxin-interacting protein (TXNIP), a redox-sensitive transcription factor, is characterized as a tumor suppressor gene and induced by cellular stress conditions." (PMID 30627326, 2018). "Apart from the tumor‐suppressing function of TXNIP in cancer cells, many reports have suggested that TXNIP regulates glucose homeostasis by inhibiting glucose uptake and glucose metabolism." (PMID 30168649, 2018). "While TXNIP has been known for its role in the regulation of glucose metabolism and cellular redox status, its role in tumor repression was relatively less studied." (PMID 29996811, 2018). "TXNIP has two independent mechanisms for its tumor‐suppressive effect, depending on the cell type and the environment." (PMID 30410860, 2018). "Increased TXNIP expression levels are correlated with tumor growth inhibition in breast, thyroid and renal cancer models, suggestive of a tumor suppressor function in these tissues." (PMID 30627326, 2018).